MIR4526 (microRNA 4526)
Synonyms: hsa-mir-4526; mir-4526
Gene: MicroRNA gene on chromosome 18 (13,611,114 to 13,611,200, forward strand). Ensembl gene ENSG00000263527.
Homologues: Orthologues: chimpanzee MIR4526 (100% identical).